UBE2S (ubiquitin conjugating enzyme E2 S)
Diseases named in the same sentence as UBE2S in open-access papers (continued):
Sharing a sentence is not in itself a finding about the gene and the disease.
chondrosarcoma (1 paper, 2024). A malignant cartilaginous matrix-producing mesenchymal neoplasm arising from the bone and soft tissue. "We found that the expression of UBE2S and TRIM28 was correlated with the survival of the patient with chondrosarcoma." (PMID 38267611, 2024).
COVID-19 (1 paper, 2025). A disease caused by infection with severe acute respiratory syndrome coronavirus 2. "In influenza, UBE2S, USP53, and TIMM10 were observed in this category, while in COVID-19, UBE2T, UBE2C, DTL, MT-ND2, UCHL1, and UBA52 were implicated." (PMID 41020849, 2025).
esophageal squamous cell carcinoma (1 paper, 2025). Esophageal squamous cell carcinoma (ESCC) is a type of esophageal carcinoma (EC) that can affect any part of the esophagus, but is usually located in the upper or middle third. "UBE2S, HIF‐1α, and FOXM1 in esophageal squamous cell carcinoma and their relationship with clinicopathological features." (PMID 41427004, 2025).
Fanconi anemia (1 paper, 2021). Fanconi anemia (FA) is a hereditary DNA repair disorder characterized by progressive pancytopenia with bone marrow failure, variable congenital malformations and predisposition to develop hematological or solid tumors. "The most vital pathways of UBE2S included cell cycle, spliceosome, DNA replication, progesterone-mediated oocyte maturation, oocyte meiosis, cellular senescence, mismatch repair, nucleotide excision repair, base excision repair and fanconi anemia pathway." (PMID 34123793, 2021).
gynecological cancers (1 paper, 2022). "In this study, the relationship between UBE2S and gynecological cancer, especially OV, was investigated using multi-source high-throughput data analysis." (PMID 35658829, 2022). "Our analysis revealed that UBE2S was significantly overexpressed in gynecological cancers (OV, UCEC, and CESC) at the pan-cancer level." (PMID 35658829, 2022). "Overall, this study showed the abnormally high expression of UBE2S at the pan-cancer level and gynecological cancers, especially OC." (PMID 35658829, 2022). "Based on the abnormally high expression of UBE2S in pan-gynecological cancers, the Kaplan–Meier method was performed to explore the overall survival (OS) of patients with gynecological cancer and correlate it with the prognosis of patients." (PMID 35658829, 2022).
intraepithelial neoplasia (1 paper, 2025). A precancerous neoplastic process that affects the squamous, glandular, or transitional cell epithelium without evidence of invasion. "The IHC method was carried out to observe whether there were differences in the expressions of UBE2S, HIF‐1α, and FOXM1 in low‐grade intraepithelial neoplasia (LIN), high‐grade intraepithelial neoplasia (HIN), and the normal epithelial tissues of the esophagus." (PMID 41427004, 2025).
ischaemic stroke (1 paper, 2022). "Eight hub genes (ADM, ANXA3, CARD6, CPQ, SLC22A4, UBE2S, VIM and ZFP36) were revealed to be significantly correlated with ischaemic stroke by a LASSO logistic regression and SVM-RFE machine learning methods." (PMID 35962388, 2022). "Eight hub genes (ADM, ANXA3, CARD6, CPQ, SLC22A4, UBE2S, VIM and ZFP36) were revealed to be significantly correlated with ischaemic stroke by the LASSO logistic regression and SVM-RFE algorithm." (PMID 35962388, 2022). "However, the expression levels of the UBE2S and ZFP36 genes did not significantly differ between the ischaemic stroke patients and normal subjects in the testing set." (PMID 35962388, 2022). "However, the expression levels of the CARD6, CPQ, UBE2S and ZFP36 genes did not significantly differ between the ischaemic stroke patients and normal subjects." (PMID 35962388, 2022).
lentivirus infection (1 paper, 2020). Virus diseases caused by the Lentivirus genus. "To verify this, we overexpressed Ube2s via lentivirus infection in the heart after MI/R injury." (PMID 32250966, 2020).
lipoma (1 paper, 2025). A benign, usually painless, well-circumscribed lipomatous tumor composed of adipose tissue. "Mechanistically, UBE2S interacts with TRIM21 to induce the ubiquitination of lipoma preferred partner (LPP) via K11 linkage, with LPP acting to inhibit the pro-metastatic effects of UBE2S on BCa." (PMID 40771930, 2025).
liver cancer (1 paper, 2024). An epithelial or non-epithelial malignant neoplasm that arises from the liver. "The results demonstrated the up-regulation of BOP1, CDC20, and UBE2S in liver cancer cells." (PMID 38577593, 2024).
metastatic melanoma (1 paper, 2012). A melanoma that has spread from its primary site to another anatomic site. "The expression levels of UBE2S and TMC01 but not ELMOD1 RNA in metastatic melanomas appear to be significantly associated with the survival of patients." (PMID 22536322, 2012).
Pca (1 paper, 2022). "This phenomenon suggests that UBE2S acts as an oncogene in Pca, fits to the result of pan-cancer analysis, and suggests that the ubiquitin family is involved in the pathogenesis of Pca." (PMID 36185200, 2022).
prostate adenocarcinoma (1 paper, 2022). "A significant difference in the expression of UBE2S was observed in a variety of human cancer diseases (p< 0.0001 in prostate adenocarcinoma)." (PMID 36185200, 2022).
prostate tumor (1 paper, 2026). "SETD6 KO GO Group 2 contains genes promoting prostate tumor growth and migration via regulation of ubiquitin transferases, including DCUN1D5, UBE2S, and CDC20." (PMID 41540805, 2026).
rectal cancer (1 paper, 2023). A primary or metastatic malignant neoplasm that affects the rectum. "For example, by ubiquitinating β-catenin, UBE2S promotes its expression and promotes the occurrence and development of rectal cancer." (PMID 36611207, 2023).
renal cell carcinoma (1 paper, 2024). "Renal cell carcinoma is characterized by a significant elevation of the E2-EPF (UBE2S) ubiquitin carrier protein, which is linked to a poor prognosis." (PMID 38312603, 2024).
squamous cell carcinoma (1 paper, 2020). A carcinoma arising from squamous epithelial cells. "In the current study, Ube2S was overexpressed in NSCLCs, including squamous cell carcinomas and adenocarcinomas, compared to normal lung tissues, including submucosal glands and bronchial epithelial tissues." (PMID 32038111, 2020).
cancer (41 papers, 2007 to 2025). A tumor composed of atypical neoplastic, often pleomorphic cells that invade other tissues. "There is an inverse association between the amount of UBE2S and the level of pVHL in most cancer cell lines." (PMID 41427004, 2025). "The findings suggest that UBE2S holds promise as a diagnostic and therapeutic target in multiple malignancies, thereby offering novel avenues for cancer therapy." (PMID 38312603, 2024). "In summary, our study has revealed a significant association between the overexpression of UBE2S in various types of cancer, including neurological, urological, gastrointestinal, and gynecological genital tumors, and unfavorable patient prognosis." (PMID 38312603, 2024). "UBE2S was found to be aberrantly expressed in almost all human cancers in a previous pan-cancer study, and elevated UBE2S expression was unfavorably associated with prognosis and pathological stage." (PMID 38028548, 2023). "UBE2S was aberrantly expressed in almost all human cancers, and elevated UBE2S expression was unfavorably associated with the clinical pathological stage and prognosis." (PMID 35578600, 2022). "It is revealed that UBE2S was mainly expressed in T cells, scar‐associated macrophages (SAMs), malignant lymphatic vascular endothelial (LVECm) cells, and carcinoma cells." (PMID 34726341, 2021). "The second network contained 6 of the identified autoantigens (AGO1, CSNK1G1, IFIT5, PHC3, SRP19, and UBE2S) out of the 35 molecules associated with cancer, organismal injury and abnormalities." (PMID 31494269, 2019). "Overexpression of ubiquitin-conjugating enzyme E2S (UBE2S) in malignant tumors has been linked to tumor growth, invasion and metastasis." (PMID 29562639, 2018). "Ube2s is an essential component of the ubiquitin-protein conjugation system, which is implicated in various cancer forms." (PMID 17490475, 2007). "Consequently, there is a pressing need to investigate the potential prognostic significance of UBE2S in pan-cancer patients, and to elucidate the underlying molecular mechanisms governing its biological function and regulation." (PMID 38312603, 2024). "Additionally, UBE2S drives the proliferation, migration, and invasion of breast, glioma, liver, and other malignant tumor cells and is associated with poor prognosis." (PMID 35658829, 2022). "Conversely, UBE2S overexpression destabilizes cell cycle inhibitors and contributes to cancer cell proliferation." (PMID 39851497, 2025). "Significantly, our findings indicate a close association between the plentiful functions and signaling pathways of UBE2S in pan-cancer and the regulation of cell cycle and repair of DNA damage, which are of fundamental significance in numerous human tumors." (PMID 38312603, 2024). "The present study utilized GO (Gene Ontology) and KEGG (Kyoto Encyclopedia of Genes and Genomes) analyses to study the possible biological functions and corresponding molecular mechanisms of UBE2S at the pan-cancer level." (PMID 38312603, 2024). "The modification of β-catenin by UBE2S resulted in increased stability and accumulation within cancer cells, ultimately promoting cancer progression." (PMID 38312603, 2024). "This research demonstrates the effects of UBE2S in 3 important cancers of the female reproductive system (cervical, endometrial, and ovarian)." (PMID 38312603, 2024). "Presently, mounting evidence suggests that UBE2S impacts cancer progression through multiple mechanisms, such as NF-κB, Cell cycle, SOX6-Catenin, Wnt/β-catenin, PI3K/AKT/mTOR, PTEN-AKT, and VHL/HIF-1α/STAT3." (PMID 38312603, 2024). "The overexpression of UBE2S in cancer cells has been shown to significantly increase the β-catenin expression, including MMP7 and cyclin D1 proteins." (PMID 38312603, 2024). "In this study, the expression level of UBE2S gene in various cancers, that is, pan-cancer, was evaluated by nucleic acid level, protein level, and cell level analysis." (PMID 38312603, 2024).
cancer (continued). "The protein expression level of UBE2S at the pan-cancer level was investigated with the help of the HPA (Human Protein Atlas) database." (PMID 38312603, 2024). "An elevated level of UBE2S expression facilitates the migratory and invasive capabilities of cancer cells according to the findings of the study." (PMID 38312603, 2024). "The current research on UBE2S genes in various human tumors lacks comprehensive integration of their roles across different cancer types." (PMID 38312603, 2024). "This review provides a comprehensive analysis of the structural characteristics of UBE2S and its potential utility as a biomarker in diverse cancer types." (PMID 38312603, 2024). "The pivotal contribution of UBE2S in various facets of cancer progression, particularly in treatment resistance, has been progressively established." (PMID 38312603, 2024). "The bridge ubiquitin-conjugating enzyme, UBE2S, of the ubiquitin system has gained attention owing to its abnormally high expression in many human malignant tumors and its close relationship with patients' prognoses and treatment responses." (PMID 38115063, 2023). "According to the experimental results, UBE2S was found to be overexpressed in cisplatin-resistant cancers." (PMID 38115063, 2023). "Recently, many studies have indicated that UBE2S is overexpressed in multiple human primary cancers and is involved in tumorigenesis." (PMID 37563971, 2023). "Ubiquitin-conjugating enzyme E2S (UBE2S) has been reported to be upregulated in various human cancers and correlates with a poor prognosis." (PMID 37422473, 2023). "The expression and prognostic significance of UBE2S at the pan-cancer level were investigated through high-throughput gene expression analysis and clinical prognostic data from TCGA, GEPIA, and GEO databases." (PMID 35658829, 2022). "Previous studies have found that UBE2S is highly expressed in several cancers and promotes tumorigenesis via invasion and cell cycle acceleration." (PMID 35637955, 2022). "In this pan-cancer study, we first delineated the mRNA expression profile of UBE2S and its correlation with the tumor pathological stage." (PMID 35578600, 2022). "The present pan-cancer study was intended to decipher the landscape of UBE2S in pathologic, immunological, and therapeutic aspects across various cancers." (PMID 35578600, 2022). "The UBE2S protein was recently described as an oncogene with potential as a therapeutic target in various cancers." (PMID 36293188, 2022). "In this study, we intended to conduct a visual analysis by using various bioinformatics algorithms at a systematic pan-cancer level to identify the expression patterns of UBE2S and determine the prognostic value of UBE2S across cancers." (PMID 35578600, 2022). "Several ubiquitin enzymes, including FBXW2, TRIM33 and UBE2S, are identified as regulators of β-catenin in cancers 20-22." (PMID 35637955, 2022). "At the pan-cancer level, UBE2S showed an abnormally high expression and considerable genetic alteration and copy number variation, especially in OV." (PMID 35658829, 2022). "Additional experimental studies are required to decipher the detailed carcinogenic mechanism of UBE2S in such detected signaling pathways in cancers." (PMID 35578600, 2022). "Gene expression analysis on 33 types of human tumor tissues and corresponding normal tissues indicated that UBE2S expressed higher in 18 types of cancer tissues based on the GEPIA database." (PMID 35658829, 2022).
cancer (continued). "Previous works have illustrated that distinct UBE2S elevation is harbored in multiple human cancers, and aberrant UBE2S expression is responsible for carcinogenicity, cell cycle disruption, drug resistance, and attenuation of ischemia-reperfusion injury (IRI)." (PMID 35578600, 2022). "In cervical cancer, UBE2S increased cancer cell invasion through EMT signalling activation and MMP-9 expression." (PMID 35637955, 2022). "Our current study discovered that upregulation of UBE2S dramatically promoted tumor stemness in nearly all analyzed cancers including LGG, TGCT, READ, LUAD, UCEC, DLBC, and BRCA." (PMID 35578600, 2022). "UBE2S, as an E2-conjugating enzyme, has been reported to be upregulated in several cancers and to promote tumour development via ubiquitination." (PMID 35637955, 2022). "Our study provided meaningful clues to support UBE2S as an immune-oncogenic molecule and shed light on potential applications of UBE2S in cancer detection, prognostic prediction, and therapeutic response assessment." (PMID 35578600, 2022). "To exam the expression of UBE2S, we explored the expression profile of UBE2S in the TCGA datasets and the UBE2S was highly expressed in various types of cancer." (PMID 34535173, 2021). "In contrast, the blockade of β-catenin resulted in the suppression of UBE2S-enhanced cancer cell growth." (PMID 34199813, 2021). "Large scale meta-analysis of cancer microarray data show that UBE2S is a commonly activated gene in multiple cancers." (PMID 34123793, 2021). "UBE2S is involved in multiple processes and mediates development and progression of malignant tumors." (PMID 34123793, 2021). "Dysregulation of UBE2S has been found in various cancers, including breast, endometrial, lung, liver, and colorectal cancer." (PMID 34199813, 2021). "The ubiquitin-binding enzyme E2S (UBE2S) has important functions in the development of human cancer." (PMID 34651050, 2021). "Past years have reported that UBE2S is preternaturally expressed in kinds of cancers and negatively relates with patients progress." (PMID 34384030, 2021). "UBE2S, a 24 kDa ubiquitin-conjugating enzyme, is highly expressed in most human cancers, including breast cancer, colon tumors, and ovarian cancer, compared with normal tissues, implying that it is involved in oncogenesis." (PMID 34123793, 2021). "Ubiquitin-conjugating enzyme E2S (UBE2S) has been proved to promote malignant behaviors in many cancers." (PMID 34535173, 2021). "The positive rate of Ube2S in cancer tissues was 59.8% (61/102), which was significantly higher than that in normal lung tissues (p < 0.05)." (PMID 32038111, 2020). "We selected A549 cells, which exhibited median Ube2S expression, for further investigation of the roles of Ube2S in cancer cells." (PMID 32038111, 2020). "Elevated Ube2S expression significantly correlated with clinical progression of cancer (TNM III versus I + II)." (PMID 32038111, 2020). "The luciferase assay showed that Ube2S significantly upregulated the activity of the canonical Wnt pathway in cancer cells (p < 0.05)." (PMID 32038111, 2020). "In Yoshimura's study, P21 was regulated by Ube2S, which can explain its impact on cancer cell proliferation." (PMID 32038111, 2020). "Ube2S overexpression, by transfecting cDNA into cancer cells, significantly upregulated the expression of β-catenin, cyclin D1, and MMP7 proteins, novel members of the canonical Wnt signaling pathway (p < 0.05)." (PMID 32038111, 2020). "We next investigated the molecules and pathways involved in the regulation of cancer cell biology by Ube2S." (PMID 32038111, 2020). "ETC-159, an inhibitor of the Wnt/β-catenin pathway, significantly inhibited the ability of Ube2S to regulate cancer cell biology." (PMID 32038111, 2020). "Ubiquitin conjugating enzyme E2S (Ube2S) plays important roles in cancer development in some malignant tumors." (PMID 32038111, 2020).